NGF (nerve growth factor)
Diseases named in the same sentence as NGF in open-access papers (continued):
Sharing a sentence is not in itself a finding about the gene and the disease.
schizophrenia (continued). "A few recent studies demonstrated reduced NGF blood levels in the first-episode schizophrenia patients compared to healthy individuals." (PMID 28358316, 2017). "The neurotrophic factors best known for their association with schizophrenia are Brain-derived Neurotrophic Factor (BDNF), Nerve Growth Factor (NGF), and neurotrophin-3 (NT-3)." (PMID 22457764, 2012). "Previous studies have reported alterations in the expression of plasticity-associated genes such as BDNF, NGF, VEGF, and NRG1 in the blood of individuals with schizophrenia, which may provide new evidence for synaptic plasticity dysfunction in schizophrenia." (PMID 37990254, 2023). "While a previous meta-analysis showed robustly decreased blood NGF in schizophrenia patients compared to controls, this was only observed in drug-naïve patients in our analysis with stricter inclusion and exclusion criteria, despite including more recent studies." (PMID 37692299, 2023). "Additionally, meta-analyses showed that blood BDNF and NGF levels were significantly decreased in schizophrenia patients when compared with controls." (PMID 33420109, 2021). "There is mounting evidence for this hypothesis, hinting at NGF signaling acting via different mechanisms in schizophrenia." (PMID 31105606, 2019). "A disturbed blood–brain barrier in schizophrenia patients is discussed to contribute to the development of neuromorphological changes, maybe thereby provoking the raising of NGF autoantibodies." (PMID 31105606, 2019). "Low expression of NGF in prefrontal cortex and low levels of BDNF in hippocampus, measured in rodent models of schizophrenia, may indicate that they are associated with cognitive impairment during disease progress and its therapy with antipsychotic drugs." (PMID 28881851, 2017). "In addition, an association between different NGF (rs6330, rs4839435) and NGFR (rrs11466155, rs2072446, rs734194) polymorphisms and schizophrenia were also found." (PMID 28358316, 2017). "Moreover, EGR3 is a downstream gene of many signaling pathways including pathways triggered by NGF, BDNF and NRG1, of which BDNF and NRG1 are schizophrenia susceptibility genes." (PMID 20156358, 2010). "However, NGF levels tended to be reduced in schizophrenia patients." (PMID 31105606, 2019). "Thus, changes of NGF levels might be involved in the formation of structural brain alternation of schizophrenia." (PMID 31105606, 2019). "Thus, the pontine cluster that was positively correlated with NGF serum levels might be a neuroanatomical correlate of NGF-mediated altered pain sensitivity in schizophrenia patients." (PMID 31105606, 2019). "Studies have shown significantly reduced brain-derived neurotrophic factor (BDNF), nerve growth factor (NGF), and NGF receptor (NGFR ) levels in the prefrontal cortex (PFC) and the cerebrospinal fluid (CSF) of subjects diagnosed with schizophrenia." (PMID 36979236, 2023). "Subsequent conjunction analysis revealed an overlap (k = 60) between the NGF serum level to GMV correlation and the GMV group comparison in the left MCC in schizophrenia patients." (PMID 31105606, 2019). "Serum NGF was significantly correlated to GMV in the left prefrontal lobe, the left midcingulate cortex, and the brainstem in schizophrenia patients." (PMID 31105606, 2019). "In this study, we found evidence for a correlation between NGF serum levels and GMV in the left prefrontal lobe, the left MCC, and the brainstem in schizophrenia patients." (PMID 31105606, 2019). "Finding a positive correlation of serum NGF to a neuroanatomical area involved in pain management may conversely suggest an influence of altered, more precisely in terms of reduced, NGF serum levels in diminished pain perception that can be observed in schizophrenia patients." (PMID 31105606, 2019).
schizophrenia (continued). "Finding the cingulate gyrus volume additionally correlated to NGF serum levels indicates an exceptional sensitivity for structural changes and supports the hypothesis of NGF signaling playing a central role in the pathogenesis of brain structural differences in a core region of schizophrenia." (PMID 31105606, 2019). "Decrease in NGF and NGF receptor (NGFR) blood levels was confirmed in drug-naïve schizophrenia patients and patients treated with haloperidol." (PMID 28358316, 2017). "As a result of the study, new information was obtained on the immuno-inflammatory profile and the levels of key regulatory cytokines IL-10 and IL-12p40, as well as neurotrophin NGF in patients with paranoid schizophrenia with severe negative symptoms." (PMID 35265356, 2021). "Recent evidence points to a sufficient correlation between peripheral and central nervous NGF levels, whereas this correlation was only shown in healthy controls but not in schizophrenia patients." (PMID 31105606, 2019). "Furthermore, a potential overlap between the results of a whole brain correlation analysis between GMV and NGF serum levels and the results of GMV reductions in schizophrenia patients were identified in a conjunction analysis." (PMID 31105606, 2019). "Remarkably, the GMV in the left MCC was reduced in our group comparison of schizophrenia patients and healthy controls and additionally was shown to be negatively correlated to NGF serum levels in schizophrenia patients, but not in healthy controls." (PMID 31105606, 2019). "In this pilot study, we investigated whether there was a correlation between NGF serum levels and gray matter volume (GMV) in schizophrenia patients." (PMID 31105606, 2019). "Our pilot study offered hints about the influence of serum NGF on the brain structure of several regions in schizophrenia patients, while no comparable results had been found in healthy controls." (PMID 31105606, 2019). "Years of education were significantly correlated to NGF serum levels in controls (rs = −.697, p = .001), but not in schizophrenia patients." (PMID 31105606, 2019). "When antischizophrenic drugs, e.g., olanzapine and lurasidone, are administered to drug-naive patients, NGF levels along with other neurotrophic factors, e.g., BDNF and NT-3, are increased, which supports the essential role of neurodegenerative disorders in schizophrenia etiopathogenesis." (PMID 40783715, 2025). "NGF serum levels were not symmetrically distributed in schizophrenia patients." (PMID 31105606, 2019). "However, it should be noted that significant correlations between NGF serum levels and brain structure were found only for schizophrenia patients and not in healthy controls." (PMID 31105606, 2019). "Thus, the high NGF level in paranoid schizophrenia patients with severe negative symptoms may be a mechanism for the development of the symptoms." (PMID 35265356, 2021).
Pruritus (27 papers, 2007 to 2025). Pruritus is an itch or a sensation that makes a person want to scratch. "Recent studies illustrated that microinjection of NGF can sensitize nociceptors causing local hyperalgesia and sensitize the skin to pruritus perception." (PMID 36012289, 2022). "NGF is associated with the severity of pruritus in atopic dermatitis, and serum NGF levels are elevated in patients with SS." (PMID 29915722, 2018). "Nerve growth factor (NGF), a neurotrophin associated with pruritus, is known to follow a circadian rhythm." (PMID 27011178, 2016). "The enhanced expression of NGF is supposedly associated with pruritus in SS." (PMID 29915722, 2018). "As NGF expression is linked with inflammation and pruritus we analyzed if amarogentin could block the release of NGF." (PMID 26600671, 2015). "The production of nerve growth factor (NGF) as a peripheral mediator of pruritus seen in wild-type mice following the induction of dry skin-resembling lesions is also absent in TLR3−/− mice." (PMID 40007792, 2025). "Mast cells secrete histamine and nerve growth factor (NGF) from preformed granules, forming histamine-driven pruritus." (PMID 37895153, 2023). "Nerve growth factor (NGF) is produced by keratinocytes, stimulates nerve fibers growth, and is associated with the severity of pruritus." (PMID 35055124, 2022). "In NGF-sensitized human skin, chemically induced itch was investigated previously showing that HIS-dependent itch is not altered by the pre-treatment." (PMID 34728705, 2021). "Keratinocytes release inflammatory mediators, such as TSLP, which in turn stimulates Th2 response and promotes production of IL-13 and IL-31, and those in conjunction with nerve growth factor (NGF), and substance P represents strong pruritus mediators." (PMID 33074181, 2020). "Abnormal NGF production induces pruritus through the sensitization of the peripheral sensory nerve terminals in the skin, the majority of which express TrkA." (PMID 31694615, 2019). "In conclusion, our study demonstrates that increased ZAP70 participates in the development of dry skin in elder pruritus via secretion of IL-2 and NGF." (PMID 27195291, 2016). "In this study, we examined inhibitory activities of YKH against nerve elongation, a Kampo formula is reported clinically to be effective in the treatment of pruritus, by means of NGF-induced neurite growth in cultured rat DRG neurons in vitro." (PMID 26287150, 2015). "NGF can induce histamine release from mast cells, and histamine enhances further production and secretion of NGF by keratinocytes, which results in a cyclic relationship between histamine and NGF, forming histamine-driven pruritus." (PMID 37895153, 2023). "Although speculative, the pruritus could reflect the human condition of paraesthesias (abnormal sensation), a reported adverse effect with anti‐NGF therapy in humans." (PMID 34724255, 2021). "In order to specifically test whether the elevated NGF-levels found in clinical inflammatory itch conditions are sufficient to facilitate itch in humans, we sensitized skin nociceptors in healthy subjects with NGF and assessed pruritogen-induced sensations." (PMID 34728705, 2021). "In addition to these mediators, proteases (e.g., kallikreins, tryptase, endogenous/exogenous proteases), neuropeptides (e.g., substance P), and neurotrophic factors (nerve growth factor (NGF), artemin) are considered to contribute to pruritus." (PMID 32290423, 2020). "Inhibition of NGF-TrkA is a known strategy for the treatment of pruritus." (PMID 31694615, 2019). "Another study showed that increased ZAP70 is involved in dry skin in elderly pruritus, while increased secretion of IL-2 and NGF may induce dry-skin itching." (PMID 30018382, 2018). "One hypothesis suggested that NGF could, therefore, play a role in the pathogenesis of nocturnal pruritus." (PMID 27011178, 2016). "Thus, inhibition of the NGF-TrkA pathway is an effective strategy for treating pruritus." (PMID 31694615, 2019).
Pruritus (continued). "Nerve growth factor (NGF) lowers the itch threshold via neuronal elongation, and thus contributes indirectly to the aggravation of pruritus." (PMID 31294123, 2019). "In the skin of psoriatic patients suffering from pruritus an overexpression of the neuropeptide receptors for SP (NK1R) and CGRP as well as of NGF and its high affinity receptor Trk-A was found." (PMID 30560129, 2018). "The efficacy of topical CT327 or of other NGF-targeting therapies has not yet been explored in the treatment of CTCL pruritus." (PMID 37555911, 2023). "There is growing evidence that cutaneous NGF-TrkA-TRPV1 signaling might be a key mechanism contributing to neurogenic inflammation and pruritus in different dermatological diseases." (PMID 33681256, 2021). "Apparently, molecular and neuronal pathways specific for BAM8–22-induced itch are not affected by NGF sensitization." (PMID 34728705, 2021). "The release of tryptase from mast cells by NGF, eventually activating PAR2 on sensory nerves, thus, may also play a role in pruritus of AD." (PMID 30560129, 2018). "Since an overexpression of NGF in BRP patients was shown, this could be a plausible explanation for the higher entry level in the NPNL area of BRP patients after chemical pruritus induction in our case." (PMID 37795274, 2023).
interstitial cystitis (26 papers, 2008 to 2026). A rare chronic debilitating urogenital disease characterized by urinary frequency, urgency, and pelvic pain. "In conclusion, this study identified increased age, CD117 expression, P2X3R expression, NGF expression, and TrkA expression as independent risk factors associated with poor short-term prognosis in patients with interstitial cystitis." (PMID 38098081, 2023). "It was shown that NGF is directly associated with pelvic pain and more specifically with dysmenorrhea, dyspareunia, painful bladder syndrome and irritable bowel syndrome." (PMID 36120440, 2022). "Age, CD117, P2X3R, NGF, and TrkA are independent prognostic factors for bladder pain syndrome/interstitial cystitis." (PMID 38098081, 2023). "Urinary NGF secreted by urothelium and smooth muscles was considered as a new biomarker of lower urinary tract disorders such as interstitial cystitis, OAB, bladder outlet obstructions and chronic prostatitis." (PMID 35373950, 2022). "In interstitial cystitis, it has been shown that there is significant neuro-inflammation involving mast cells via different signals (nerve growth factor (NGF), substance P (SP)) and leading to the “suffering” of nerve fibers." (PMID 35163758, 2022). "Nerve growth factor (NGF) is thought to play a key role in chronic pain felt by bladder pain syndrome/interstitial cystitis (BPS/IC) patients by activating its high affinity receptor tropomyosin-related kinase subtype A (Trk A)." (PMID 31575913, 2019). "This study was designed to evaluate the efficacy and safety of fulranumab, a fully human monoclonal antibody directed against nerve growth factor (NGF), for pain relief in patients with interstitial cystitis/bladder pain syndrome (IC/BPS)." (PMID 28056917, 2017). "The level of NGF in bladder pain and interstitial cystitis were inconsistent among previous studies." (PMID 27462520, 2016). "Increased NGF levels have been observed in the urine of patients with interstitial cystitis and painful bladder contractions." (PMID 25954993, 2015). "Increased NGF content was detected in the urothelium of biopsies obtained from women with bladder pain syndrome (BPS) while increased NGF, neurotrophin-3, and glial cell line–derived neurotrophic factor were found in the urine of BPS patients." (PMID 24788240, 2014). "Previous studies have shown a significant increase of TRPV1-IR nerve fibers in inflammatory conditions that elicit pain, such as painful bladder syndrome and vulvodynia, and are believed to involve NGF." (PMID 18267041, 2008). "Lastly, mast cell and immune cell activation, along with the release of inflammatory mediators such as histamine, substance P, nerve growth factor (NGF), and estrogen, can stimulate the demyelinating nerve fibers of the bladder, resulting in bladder pain syndrome." (PMID 38098081, 2023). "To examine whether urinary nerve growth factor (NGF) could serve as a biomarker for interstitial cystitis/painful bladder syndrome (IC/PBS), we conducted a comprehensive meta-analysis of 9 studies." (PMID 25181532, 2014). "Urinary NGF is also increased in interstitial cystitis/bladder pain syndrome." (PMID 22654715, 2011). "On the other hand, NGF level was found to be elevated in bladders in pathological states such as OAB, bladder pain syndrome, idiopathic and neurogenic DO, bladder oversensitivity, and bladder outflow obstruction." (PMID 30155683, 2019). "Partly in agreement with these observations, another group observed a decrease in urinary NGF but not BDNF in patients with interstitial cystitis/bladder pain syndrome treated with hyaluronic acid." (PMID 38785946, 2024).
ischemic stroke (26 papers, 2011 to 2026). A stroke disorder caused by obstruction of blood flow to the brain, due to thrombotic (local blood clot formation) or embolic (due to a blood clot or other material traveling from another site) event. "A more intriguing task is the possible application of NGF agonists and mimetics in the acute period of ischemic stroke and traumatic brain injury (TBI)." (PMID 41562905, 2025). "Specific variants of NGF (NGF rs6330, NGFR rs2072446/rs734194) can modulate ischemic stroke susceptibility." (PMID 41562905, 2025). "Elevated BDNF and NGF in peripheral blood is one of the important factors for TMS to promote cognitive function recovery in ischemic stroke patients." (PMID 40948655, 2025). "This study aimed to evaluate the effectiveness and safety profile of specific stimulation mode SMES combined with NGF used in the treatment of ischaemic stroke during the recovery period." (PMID 39033586, 2024). "Under strict quality control, this study will potentially confirm the clinical efficacy of specific stimulation mode SMES combined with NGF for the recovery period of ischaemic stroke." (PMID 39033586, 2024). "Further, this study innovatively combines SMES and NGF to treat patients with ischaemic stroke during convalescence and, thus, will provide a new treatment method with sufficient clinical evidence." (PMID 39033586, 2024). "As for ischemic stroke, the longest intranasal NGF treatment was six days in rats (post MCAo – middle cerebral artery occlusion -)." (PMID 35928573, 2022). "Further, the transplantation of BRCA1-transfected NSCs into mice with ischemic stroke increased brain-derived neurotropic factor and nerve growth factor expression in the brain and elicited neurological function improvement." (PMID 31073355, 2019). "Recent study showed that NGF-enhanced angiogenesis contributed to neurological functional recovery after ischemic stroke via the initiation of PI3K/Akt signaling pathway." (PMID 31920923, 2019). "In the present study, we evaluated the association of the functional polymorphisms in NGF (rs6330) and NGFR (rs2072446 and rs734194) genes with ischemic stroke in an Armenian population." (PMID 29499660, 2018). "The paracrine factors produced by BMCSs such as VEGF, BDNF, and NGF have a neuroprotective potential in animal ischemic stroke models." (PMID 27517324, 2016). "Delivery of NGF across the BBB by SMES may be effective for treating dysphagia after ischemic stroke." (PMID 41929605, 2026). "Hence, the authors conducted a multicentre, randomized, placebo-controlled, assessor-blinded clinical trial to assess the effectiveness and safety of SMES combined with NGF treatment used during ischaemic stroke recovery." (PMID 39033586, 2024). "In addition, MSC transplantation significantly enhanced the mRNA expression of BDNF and nerve growth factor (NGF) in ischemic stroke rat models." (PMID 38785945, 2024). "However, NGF is mainly used for the treatment of peripheral neuropathy and is rarely used during the recovery period of ischaemic stroke." (PMID 39033586, 2024). "•This protocol describes a multicentre, randomized, placebo-controlled trial that aims to assess the efficacy and safety of specific stimulation mode SMES combined with NGF in reducing the recovery period of ischaemic stroke and provide evidence-based medical data." (PMID 39033586, 2024). "Another preclinical experiment confirmed that exosomes that transported NGF could reach the ischemic area to promote the recovery from ischemic stroke." (PMID 34307384, 2021). "Our current study revealed that R1 treatment significantly increased the expression of BDNF, NGF and NT-4 after ischemic stroke, and these results are similar to a previous report on the promotion of neurogenesis following the overexpression of adenoviral-transduced BDNF mRNA." (PMID 34025400, 2021). "Exercise-induced NGF expression could therefore play a role in reducing brain injury around 4 weeks after ischaemic stroke." (PMID 20726846, 2011).